FOSB (FosB proto-oncogene, AP-1 transcription factor subunit)
Diseases named in the same sentence as FOSB in open-access papers (continued):
Sharing a sentence is not in itself a finding about the gene and the disease.
cancer (65 papers, 2011 to 2025). A tumor composed of atypical neoplastic, often pleomorphic cells that invade other tissues. "Furthermore, high extracellular Ca2+ also stimulated the expression of early response genes such as FOS/FOSB and a unique set of genes associated with malignant tumors, including MAGEC2." (PMID 35355564, 2022). "Interestingly, overexpression of PTCH1, ABL1 and FOSB genes are reported to be associated with a low survival rate among cancer patients." (PMID 36704357, 2022). "Based on the microarray data, we speculated that the expression of early response FOS and/or FOSB may lead to the expression of cancer progression associated genes such as MAGEC2." (PMID 35355564, 2022). "An earlier study showed that doxorubicin causes histone eviction and transcriptome alterations in cancer cells; therefore, FOSB may be a suitable biomarker for the response to anthracyclines in BC cells." (PMID 27248170, 2016). "FOSB has influenced biological functions of various cancer cells, including apoptosis, migration and proliferation." (PMID 41272900, 2025). "Recently, it was shown that components of the AP-1 transcription factor (FOS, FOSB, JUN), EGR1, and NR4A1 behave as a conserved co-regulated group of genes whose expression is associated with ZFP36 in cancer cells." (PMID 39026155, 2024). "In contrast, ginsenoside Rg1 downregulated the mRNA expression of ARG2, MMP1, S100A4, and RAPSN, and upregulated the mRNA expression of LAMC2, DSC2, KRT6A, and FOSB, thereby enhancing the anti-cancer function of granulocytes inhibited by NA." (PMID 36817446, 2023). "c-Jun, c-Fos, NFКB, JunB, EGR-1 and FosB by qRT-PCR after treating PBMCs with cfChPs (10ng) isolated from sera of cancer patients." (PMID 38274821, 2023). "The FOSB gene codes for the FosB proto-oncogene, AP-1 transcription factor, which can activate cell proliferation, differentiation, and transformation in cancer cells." (PMID 37834191, 2023). "Collating our in vitro and in vivo data, this suggested that drug-induced FOSB induction is a potential mechanism of acquired resistance to SCD inhibitors in cancer." (PMID 33568479, 2021). "Our finding that a single TF FOSB controls the transcriptional overdrive of SCD in AqR cells in two unrelated cancers is notable." (PMID 33568479, 2021). "Li H.’s study also confirmed that the overexpression of FOSB protein can promote the proliferation of cancer cells." (PMID 34238253, 2021). "Noteworthy, among the top-10 upregulated genes we found cancer-related genes such as FosB proto-oncogene (FOSB; logFC = 1.89), mesothelin (MSLN; logFC = 3.06), and arrestin beta 1 (ARRB1; logFC = 1.89)." (PMID 34439473, 2021). "Genetic and epigenetic mechanisms determine SCD inhibitor sensitivity and acquired resistance through FOSB in cancer." (PMID 33568479, 2021). "This analysis found that AC009283.1 knockdown altered the expression of NOTCH3, TNFa and FOSB, genes that have been previously suggested to be drivers for proliferation and cell cycle in cancer." (PMID 32753692, 2020). "Among these genes, EGR1, Fos Proto-Oncogene (FOS), FosB Proto-Oncogene (FOSB), Jun Proto-Oncogene (JUN), Dual Specificity Phosphatase 6 (DUSP6) and CTGF have been previously implicated in cancer metastasis." (PMID 30792382, 2019). "We detect spatial proximity of areas consisting of apparent cancer glands (“FOSB-enriched”), inflammation (“AQP3-enriched”) and reactive stroma (“NR4A1-enriched”)." (PMID 29925878, 2018). "We found 237 differentially expressed genes (DEGs) including EGR1, FOS, and FOSB, which were three cancer-related transcription factors." (PMID 30228980, 2018). "In fact, TP4 treatment was shown to activate the stress-induced transcription factor, FOSB, to trigger necrotic death in cancer cells." (PMID 30469546, 2018). "Using multiple cohorts profile datasets and integrated bioinformatical analysis, we identified commonly 237 DEGs, and finally found EGR1, FOS, and FOSB, 3 cancer-related TFs, which were downregulated in HCC." (PMID 30228980, 2018).
cancer (continued). "Stroma and normal cells separate from inflammation, however, compared to the previous clustering reactive stroma is more similar to inflammation and cancer glands (“FOSB enriched”) than stroma cells." (PMID 29925878, 2018). "IPA analysis of these unique up-regulated genes indicated that some genes were associated with cell transformation during cancer progression (ABL1, TRIO, FOSB, NRCAM, TRIB2 and CDK6) and others with cell survival (e.g., BCL10, BBC3, FGF8, HSPA4 and SOD1)." (PMID 29137349, 2017). "FOSB can form a transcription factor complex, AP-1, which can control invasion of tumors and has been reported to promote metastasis in other cancers." (PMID 27821810, 2016). "AP1 (jun/fos) transcription factors (c-jun, junB, junD, c-fos, FosB, Fra-1, and Fra-2) are key regulators of epidermal keratinocyte survival and differentiation and important drivers of cancer development." (PMID 23762562, 2013). "Notably, MP7 was associated with stress meta program (MP5) in pan‐cancer studies, sharing 14 common genes, including ATF3, EGR1, FOSB, GADD45B and NR4A1." (PMID 40292733, 2025). "Importantly, the downregulation of HB-EGF in SCC154 is enough to block the upregulation of JUNB, FOS and FOSB when cancer cells and CAFs are co-cultured." (PMID 39262776, 2024). "The downregulation of FosB has been shown to be negatively correlated with the cancer grade." (PMID 38966281, 2024). "In addition to TERT, BLCAP, and KBTBD8, we also observed low levels of damage induction in UV-irradiated melanocytes at a number of other recurrent mutations in the promoters of known or suspected cancer genes (i.e., TCF3, TOP2A, NUMB, FOSB, and OTUB2)." (PMID 37169747, 2023). "The radioresistance of cancer cells was blocked by TP73 overexpression or FOSB knockdown." (PMID 37173692, 2023). "In addition, SETDB1-mediated expression of FOSB/AP-1, a common target gene, is involved in diverse cancers." (PMID 35497876, 2022). "It has also been reported that FOSB could exert a functional role in modulating the proliferation of cancer cells through regulating miR-22 expression, suggesting the potential targeting relationship between FOSB and miR-22." (PMID 35497876, 2022). "Interestingly, PTCH1 shows the highest mutation rate in 7% (127/1867; 7%) of cancers, followed by PDGFRA (89/1867; 5%), ABL1 (68/1867; 4%), FOSB (56/1,678, 3%), ALDH1A1 and CCND2 (48/1,678; 2.9%), (55/1867; 2.9%)." (PMID 36704357, 2022). "The results above suggested that EGR1, FOS, and FOSB, three cancer-related TFs, could play an important role in the progression of HCC." (PMID 30228980, 2018). "Collectively these data demonstrate overexpression of EINCR1 leads to defects in the induction of EGF-activated protein coding genes and likely explains the reciprocal relationship between EINCR1 expression and the expression of genes like FOS and FOSB in cancer cells." (PMID 28732076, 2017). "Anthracyclines, but not taxane-based drugs, strongly induce FOSB in BCs; anthracyclines kill cancer cells through causing torsional stress and nucleosome destabilization." (PMID 27248170, 2016). "We found that CBX7 negatively or positively regulates the expression of several genes (such as SPP1, SPINK1, STEAP1, and FOS, FOSB, EGR1, respectively) associated to cancer progression, by interacting with their promoter regions and modulating their transcriptional activity." (PMID 24865347, 2014). "However, polymorphisms (rs2282695 and rs12373539) of the FOSB gene have not been reported to be associated with susceptibility to cancers." (PMID 23181129, 2012). "Thus, from some of the results one could argue that LH may serve as a positive regulator on cancer growth and invasion through overexpression of CCl2 and FOSB." (PMID 21711548, 2011). "In the aging model group, the genes that were highly expressed were mainly FOSB, HS3ST2, and FSTL4, and other genes related to tumors, cancer, and other diseases." (PMID 38191526, 2024).
cancer (continued). "Previous reports using normal epithelial tissues and carcinomas revealed that warm enzymatic dissociation (i.e., at 37 °C) invoked a distinct ‘Warm Dissociation Signature’ enriched in FOS, FOSB, and JUN." (PMID 37254069, 2023). "In other studies, FOS and FOSB were found to increase cancer cell invasion, and JUN was involved in cancer cell invasion and metastasis." (PMID 35037412, 2022). "Among the top 10 DRGs identified for Korean (GSE24375), six genes are GC related (ESRRG, LIMS1, GATA3, GATA6, SOX9, POU2F1) and the other four are cancer related (IRF2, RGS3, MRPL36, FOSB)." (PMID 29745833, 2018). "Based on the results, we found that STAT6, a cancer-related TF, regulated FOS and FOSB, while FOS and EGR1 were coregulated by 2 cancer-related TFs, including BRCA1 and SP1, respectively." (PMID 30228980, 2018). "We intersected 237 common DEGs and curated 36 cancer-related TF families to get three differentially expressed TFs (EGR1, FOS, and FOSB) in HCC." (PMID 30228980, 2018). "While EINCR1 is upregulated in the cancer samples, both FOS and FOSB show reduced expression in cancer samples." (PMID 28732076, 2017). "In fact, FOS, FOSB and EGR1 are proteins that have been reported to be down-regulated in several human carcinomas suggesting a critical role of these proteins in cancer progression." (PMID 24865347, 2014). "However, in the aging model group, the genes that were highly expressed were mainly FOSB, HS3ST2, and FSTL4, which are related to tumors, cancer, and other diseases." (PMID 38191526, 2024). "Transcription factor (TF) motifs, including CEBPB (+), FOSB (+), SAP30 (+) and ATF4 (+), were significantly upregulated in CNV high cancer cells, while IRF3 (+), ETV7 (+), STAT1 (+) and IRF7 (+) were downregulated, indicating promising new regulatory networks driven by TFs in OS cells." (PMID 36596773, 2023). "Moreover, we illustrated downstream‐targeted genes of JUN, FOS, FOSB, EGR1, and ZFP36 and demonstrated that these targeted genes were involved in “positive regulation of cell death”, “pathways in cancer”, “PI3K‐Akt signaling pathway”, and so on." (PMID 35037412, 2022). "This module included a number of immediate early and growth factor response genes and overlapped with modules previously identified for SDF1 responses in PBs (genes such as CD69 and NR4A2) and growth factor responses in cancer (genes such as EGR1/3, FOS, FOSB, and IER2)." (PMID 36130130, 2022). "FOSB-driven acute phase response signaling and FOSB-mediated SCD transcription and perhaps FOSB/SCD-independent mechanisms are involved in SCD inhibitor acquired resistance in cancer." (PMID 33568479, 2021). "Since transcription factor-mediated gene transcription depends on both its accessibility to cognate binding sites and its abundance, the authors determined gene expression of JUN and FOS family members and found overexpression of FOS, FOSB, and FOSL1 in the cancer." (PMID 34722266, 2021). "Gene interaction networks related to cancer, cellular movement and growth, and TGF-β signaling pathway were used to demonstrate interactions between the identified dysregulated genes and FOSB in hiPSC-ECsSERPINE1-FOSB." (PMID 33377124, 2020). "CYP24, FOSB, PCDH10, THBS2, and RASSF5 were selected as representative genes for further analysis, as they are well-known regulators of cancer cell proliferation and apoptosis, and the results obtained by qPCR analysis were shown to support our previously obtained results." (PMID 29156803, 2017). "In particular, the expression of FOS, FOSB, and ATF3 did not correlate with the low HSF1 levels in these cancer types." (PMID 36010586, 2022).
infection (20 papers, 2013 to 2026). The state of being infected such as from the introduction of a foreign agent such as serum, vaccine, antigenic substance or organism. "This dataset displayed no significant increase in FOS, NR4A1 and FOSB gene expression (only a decrease at 48 hpi for FOSB) over the 96 h course of infection, like all other SARS‐CoV‐2 datasets." (PMID 38623540, 2024). "Identification of fosfomycin resistance protein (fosB) in both Paenibacillus and Sporosarcina genomes in this study is crucial for effective infection control measures and the development of strategies to combat the spread of antibiotic resistance." (PMID 37461605, 2023). "Indeed, the computed top DEG, typifying each cluster on day 3 in the effector phase of infection, hosted several interferon-induced anti-viral genes (Irf1, Irf7, Ifrd1, Socs1, Socs3, Ifit1, Bst2, and Isg15) as well as genes associated with mature resident Trm cells (Cd69, Nfkbid, Brd2, FosB)." (PMID 35260804, 2022). "A previous study showed that the FOSB gene was up-regulated in alveolar macrophages during the early phase of infection with a European PRRSV strain." (PMID 33618723, 2021). "Infection with SARS‐CoV, MERS‐CoV and low pathogenic HCoV‐229E evoked a partially overlapping transcriptional response, characterised by a significant and sustained increase in expression of IEGs such as FOS, NR4A1 and FOSB." (PMID 38623540, 2024). "In contrast, the ZIKVPE243 infection resulted in a lower number of significantly dysregulated genes, though a few exhibited large fold changes, including MD1, MT1P1, and FOSB." (PMID 41477009, 2025). "During an active infection, neurodegeneration can result from the persistency of pro-inflammatory markers, such as NO, ROS, IL-1ß, TNF-α, and IL-6 via AP-1 (FosB), NF-кB (RelA/NF-KBI), and Stat1 signaling in microglial cells." (PMID 38731913, 2024). "Transcriptomic analysis results showed that NC infection activated the interleukin (IL)-17 and tumor necrosis factor (TNF) signaling pathways, increasing the expression of chemokines (CXCL1/2/3) and inflammatory genes (FOSB)." (PMID 41669237, 2026). "Under Ad-vaspin infection, we observed increases in the levels of c-Fos and c-Jun but no changes in Fosl1, Fosl2, FosB, JunB or JunD." (PMID 40025171, 2025). "Many LCM-associated regulons were not altered by infection (C/EBPβ), while others were lost (RARG and MAF) and others gained (KLF4, STAT3, FOSB, and BHLHE40)." (PMID 36948193, 2023). "Moreover, by interpreting the decision patterns of our classification system, we identified that different immune cells upregulating or downregulating the expression of the genes CD3, CD14, CD16, FOSB, S100A12, and TCRɣδ can accurately differentiate between different degrees of infection." (PMID 38892107, 2024). "Furthermore, several of these IEGs such as FOS and FOSB are related to the JNK/AP‐1 pathway, which has an essential role in cell death of infected cells via apoptosis and necrosis, and is important for the cellular response to pro‐inflammatory stimuli, and thus could limit progression of infection." (PMID 38623540, 2024).
bacterial infections (2 papers, 2023). "It has been reported that fosB is significant due to its impact on the treatment of bacterial infections, the emergence of multidrug resistance, the potential for horizontal gene transfer, and its implications for public health." (PMID 37461605, 2023).
movement disorder (2 papers, 2016 to 2026). Neurological conditions resulting in abnormal voluntary or involuntary movement, which may impact the speed, fluency, quality and ease of movement. "However, the FosB/ΔFosB-expressing of levodopa liposomes group was significantly lower than the levodopa group, which suggested that application of chitosan-coated levodopa nanoliposomes may reduces the different movement disorder in PD treatment, compared to ordinary levodopa tablets." (PMID 27378167, 2016).
kidney disease (1 paper, 2023). "Previous studies have shown that FOSB can be used as a diagnostic marker for lgA kidney disease." (PMID 36923221, 2023).
neurodevelopmental disorder (1 paper, 2023). A behavioral and cognitive disorder with onset during the developmental period that involves impaired or aberrant development of intellectual, motor, or social functions. "In an attempt to explain why GIH induces behavioural manifestations of abnormal neurodevelopmental disorders in males, we also quantified FosB expression in the amygdala, but the absence of an effect within this structure indicates that this structure was not activated by GIH." (PMID 37642495, 2023).
FOSB also shares sentences with these, for which no sentence is quoted: hemangioendothelioma (6 papers); alcoholism (3); angiosarcoma (2); astrocytoma (2); cognitive deficits (2); drug dependence (2); fibrosarcoma (2); osteoporosis (2); osteosclerosis (2); soft tissue tumor (2); benign bone tumours (1); bone cancer (1); bone vascular neoplasms (1); chronic kidney disease (1); chronic obstructive pulmonary disease (1); cognitive decline (1); dependence (1); epithelioid sarcoma (1); Erythema (1); esophageal squamous cell carcinoma (1); esophageal tumor (1); fibrosis (1); giant cell tumor of bone (1); glaucoma (1); head and neck squamous cell carcinoma (1); hepatitis C (1); herpes simplex infection (1); IgA Nephropathy (1); immune disorders (1); infectious disease (1).
A further 22 diseases each share a sentence with FOSB in 1 paper.